BRCA1 (BRCA1 DNA repair associated)
Diseases named in the same sentence as BRCA1 in open-access papers (continued):
Sharing a sentence is not in itself a finding about the gene and the disease.
ovarian carcinoma (continued). "For these reasons, we assumed that the patterns and effects of BRCA1 or BRCA2 pathogenic variants related to breast or ovarian cancer in Korean are different than those of other populations (not only non-Europeans but also other Asians)." (PMID 34063308, 2021). "BRCA1 and BRCA2 genes have been constantly associated with breast and ovarian cancers." (PMID 33924591, 2021). "Inherited mutation of either BRCA1 or BRCA2 is associated with familial breast and ovarian cancer." (PMID 34359565, 2021). "Both BRCA1/2-related breast and ovarian cancers are typically highly aggressive." (PMID 32862296, 2021). "In addition, high-grade serous adenocarcinoma has been reported as a pathological feature of BRCA1/2 ovarian cancer." (PMID 32862296, 2021). "In this review, we investigated the association of ovarian cancer risk and BRCA mutation location, and differences of other BRCA-related cancer risks by BRCA1/2 mutation, and furthermore, we discussed the difference in the prevalence of germline BRCA mutation in ovarian cancer patients." (PMID 34356066, 2021). "In this study, we analyze the published data on HRT and risk for breast or ovarian cancer in BRCA1/2 mutation carriers with and without RRBSO." (PMID 33885953, 2021). "The BRCA1 mutated ovarian cell line UWB1.289 appeared to be considerably more prone to the cytostatic and cytocidal effects of the tested alkylating agents than the other ovarian cancer cell lines tested due to its BRCAness phenotype." (PMID 34440232, 2021). "To verify these characteristics, we tested BRCA1 protein levels in these ovarian cancer cell lines." (PMID 34919531, 2021). "Finally, in ovarian cancer, germline BRCA1/2 cases respond in 87–96% of cases in prospective trials." (PMID 34696429, 2021). "The AZD6738 and olaparib combination is currently being tested in phase II trials, which includes the CAPRI study for recurrent ovarian cancers (NCT03462342), as well as OLAPCO study in patients with HR defects beyond those associated with BRCA1/2 mutations (NCT02576444)." (PMID 34027408, 2021). "The mutation is associated with increased sensitivity of ovarian cancer cells to cisplatin therapy, independent of wild-type BRCA1 alleles." (PMID 34711195, 2021). "Hollis and colleagues summarized the evidence regarding the implications of different germline BRCA PVs in ovarian cancer and concluded that aberrations at particular BRCA1 sites could confer differential sensitivity to platinum-based chemotherapy and PARPi." (PMID 35875314, 2021). "This association was confirmed in breast and/or ovarian cancer families and cohorts with no known BRCA1 or BRCA2 mutations, leading to the proposition to include RAD51D and RAD51C to the list of genes screened for breast cancer predisposition." (PMID 34208195, 2021). "The clinical condition of the two families was consistent with hereditary breast and/or ovarian cancer (HBOC) but they lacked pathogenic BRCA1 or BRCA2 variants." (PMID 34638292, 2021). "The primary objective of this study was to evaluate the BRCA mutation rate in families with PrC associated with breast and/or ovarian cancers; secondary aims were to compare the characteristics of families and BRCA-related PrC outcome among BRCA1 and BRCA2 carriers." (PMID 33710808, 2021). "Additionally, BRCA1 and BRCA2 are the most common genes associated with increased risk in hereditary breast and ovarian cancer." (PMID 34855882, 2021). "PARP inhibitors are currently FDA-approved for BRCA1/2-mutant breast, prostate and ovarian cancer." (PMID 34944870, 2021). "The ratio of BRCA1 to BRCA2 mutations varies from population to population, but it is consistent with previous reports that germline BRCA1 mutation was more common than germline BRCA2 mutation in ovarian cancer cases." (PMID 34356066, 2021).
ovarian carcinoma (continued). "As a comparison in a recent study with an extended targeted panel, including 64 hereditary cancer predisposition genes, PV detection rate of 19.2% was reported in 496 patients with hereditary breast and ovarian cancer and 12% patients were positive for a PV in BRCA1 and BRCA2 genes." (PMID 34326862, 2021). "Subsequently, the studies showed that methylation of RASSF1A and BRCA1 was evident in different stages and grades of ovarian cancer and might have potential as a prognostic marker in ovarian cancer patients." (PMID 33936202, 2021). "However, as ovarian cancer can occur also before the age of 35 years and data on RRBSO in BRCA1/2 mutation carriers is still limited, the ideal timing of RRBSO remains difficult." (PMID 33885953, 2021). "Many recent reports have determined the frequency of BRCA1/2 mutation retention in patients with breast and ovarian cancers without selection bias, without considering family history, age of onset, and cancer subtype." (PMID 32862296, 2021). "For example, promoter CpG island hypermethylation is observed in BRCA1; the wild-type BRCA1 tumor suppressor gene is commonly silenced in nonfamilial breast and ovarian cancers and is associated with increased cancer invasiveness and mortality." (PMID 34988459, 2021). "In our previous study in year 2013, non-founder PV of the BRCA1/2 were identified in 4 out of 30 (13%) founder-negative, high-risk breast/ovarian cancer families." (PMID 33468216, 2021). "The presence of germline mutations in the BRCA1 and BRCA2 genes significantly increases the risk of developing breast and ovarian cancer, however only 25% of the risk of familial cancer can be attributed to pathogenetic mutations localized in the coding regions of these two genes." (PMID 34299313, 2021). "The c.1516G > T;p.E506* variant was previously reported in three BRCA1/2 negative breast and/or ovarian cancer patients and twice in ATLD cases on ClinVar." (PMID 33510186, 2021). "At least 15% of women with high‐grade nonmucinous ovarian cancers have germline mutations in BRCA1/2 and, importantly, almost 40% of these women do not have a family history of breast/ovarian cancer." (PMID 34669199, 2021). "Germline BARD1 variants appear to convey a low-moderate risk of ovarian cancer, but do not appear to explain non-BRCA1/2 breast and ovarian cancer heritability." (PMID 34680387, 2021). "This study cohort included 176 ovarian cancer patients, 109 women without cancer but with known BRCA1 mutations, and 295 healthy controls from the United Kingdom, Italy, Germany, Norway, and the Czech Republic." (PMID 34208337, 2021). "The spectrum and frequency of BRCA1/2 mutations between ovarian cancer patients have not yet been precisely established in Belarus." (PMID 33478551, 2021). "Further to this, genetic risk factors such as the presence of established predisposition genes for hereditary breast and ovarian cancer (e.g. BRCA1, BRCA2) have not been found to be prevalent in Jamaican women, compared to other Caribbean countries." (PMID 33892714, 2021). "Heritable mutations in BRCA1 and BRCA2 genes are a major risk factor for breast and ovarian cancer." (PMID 35008272, 2021). "There are some tumor types besides breast and ovarian cancer whose risk is somewhat elevated in BRCA1/2 mutation carriers, however these tumors do not always display loss-of-heterozygosity (LOH) for BRCA1/2 locus, i.e. they retain the wild-type BRCA1/2 allele." (PMID 34454564, 2021). "A recent study on suggested familial BRCA1/2 wildtype high grade ovarian cancers found that only 6.6% of cases could potentially be explained by genes known or suggested to be linked with a higher risk of ovarian cancer." (PMID 34069790, 2021).
ovarian carcinoma (continued). "In a large study involving 626 patients with ovarian cancer without selection bias, patients with 218 BRCA1/2 mutations had better 3-year short-term survival than the mutation-free group." (PMID 32862296, 2021). "Another study found that the absence of pre-existing cfDNA BRCA1/2 reversion mutations in patients with ovarian cancer who had somatic or germline BRCA1/2 mutations and were treated with rucaparib was associated with improved progression-free survival." (PMID 33520111, 2021). "Moreover, in individuals with breast and/or ovarian cancer, the BRCA1/2 status serves as an important guide for surgical treatment planning as well as medical management (chemotherapy and targeted therapy with poly (ADP-ribose) polymerase inhibitors (PARPi)." (PMID 33468216, 2021). "Further studies based on the NGS of BRCA1 and BRCA2 genes, as well as other genes that may be associated with a strong predisposition to ovarian cancer, should be carried on." (PMID 33478551, 2021). "Mutations in BRCA1 and BRCA2 are well-established risk factors for breast and ovarian cancer." (PMID 33478551, 2021). "Recently, we showed that the BRCA1 promoter is frequently hypermethylated in ovarian cancer tissue, but the methylation status is often lost in recurrent disease, suggesting a potential resistance mechanism either through therapy‐induced cancer evolution or by clonal selection." (PMID 34601813, 2021). "Interestingly, the cumulative risks of breast or ovarian cancer for Korean BRCA1 or BRCA2 carriers by region of BCCR or OCCR showed a different trend than what was previously reported." (PMID 34063308, 2021). "A wide range of 5–90% BRCA1 promoter hypermethylation among ovarian cancer cases has been reported in the past; the wide variability is possibly the consequence of different detection techniques, cohort selection criteria, and/or material sources (i.e., tissue vs. cfDNA)." (PMID 34601813, 2021). "Any family history of ovarian cancer (irrespective of number of affected family members) was associated with a germline BRCA1 variant (OR, 2.78; 95% CI, 1.59-4.87; P < .001) but not BRCA2 (OR, 1.36; 95% CI, 0.47-3.97; P = .57)." (PMID 33646313, 2021). "However, the penetrance of the BRCA1 or BRCA2 gene for ovarian cancer has been reported to be about 40% and 20%, respectively." (PMID 34356066, 2021). "BRCA1 is a drug-related gene in ovarian cancer that has received attention." (PMID 34289901, 2021). "The percentage of BRCA1/2 germline mutation carriers in Chinese NSCLC patients (86/9010 = 0.95 %) was significantly lower than that in Chinese breast and ovary cancer patients (1481/20,523 = 7.2 %) (P < 0.001), suggesting a cancer-type dependent incidence of BRCA1/2 germline mutations." (PMID 33563323, 2021). "In summary, in this study, all female members of a typical HOC family were studied, and BRCA1 (3326A>T) and BRCA2 (1342A>C) mutations were detected, which may be the causative genes of ovarian cancer in this family." (PMID 32356124, 2020). "The Belgian guidelines for managing HBOC do not recommend screening for ovarian cancer in BRCA1 or BRCA2 mutation carriers." (PMID 32655641, 2020). "We believed that screening and follow-up of BRCA1/2 gene mutations in III generation women and their offspring may have important implications for the occurrence of ovarian cancer in this family members." (PMID 32356124, 2020). "Since the identification of the BRCA1 gene in 1994 and the BRCA2 gene in 1995, clinical testing of these genes has been performed to identify people with high hereditary risk of breast and ovarian cancer." (PMID 32203205, 2020). "Olaparib administered in high-grade serous and/or undifferentiated ovarian cancer patients showed a 41% and 24% objective response rate with or without BRCA1/2 mutations; however, there was no response in TNBC patients." (PMID 32029455, 2020).
ovarian carcinoma (continued). "The comprehensive ovarian cancer genomic studies revealed that hypermethylated-BRCA1 ovarian cancer with platinum therapy had a similar prognosis as the intact BRCA cancer, whereas BRCA1/BRCA2-mutated ovarian cancer showed better prognosis than the wild-type cancer." (PMID 32269964, 2020). "In support of this, low aneuploidy in BRCA1/2 germline related breast and ovarian cancers may also suggest more active immunosurveillence against cancer associated hyperploidy." (PMID 32164626, 2020). "Interestingly, signature 3 was identified in BRCA1/2 mutations or HRD cancers, such as breast, pancreatic and ovarian cancers." (PMID 32863940, 2020). "An example of this applies to the genetic testing of BRCA1/2 in ovarian cancer." (PMID 32483276, 2020). "Additional studies are needed to elucidate the effect of CRS on prognoses in advanced-stage ovarian cancer patients with and without BRCA1/2 mutations." (PMID 32131779, 2020). "Although hundreds of mutation sites have been found in BRCA1/2, not all mutations are associated with ovarian cancer." (PMID 32356124, 2020). "A significant correlation between BRCA mutation and the risk of secondary ovarian cancer was also found (non-mutated vs. BRCA1/2-mutated tumors: 2.2% vs. 14.0%, p = 0.001)." (PMID 33019612, 2020). "Previous studies reported that BRCA1/2 downregulation might represent a potential indicator of the treatment response of PI3K inhibition in ovarian cancer cells." (PMID 32194423, 2020). "For ovarian cancer, somatic tumor profiling of BRCA1 and BRCA2 for PARP inhibitor therapy may reveal inherited germline mutations in these genes." (PMID 31937368, 2020). "The most important cancer type related with BRCA1/2 is breast and ovarian cancer." (PMID 32283892, 2020). "Indeed, high-penetrance germline mutations in DNA repair genes are important players in familial cancers: BRCA1, BRCA2 mutations or mismatch repair, and polymerase deficiency in colorectal, breast, and ovarian cancers." (PMID 32605254, 2020). "Although the BRCA2 gene mutation was not documented, we found that 10.4% of patients with ovarian carcinoma other than mucinous carcinoma carry the BRCA1 gene mutation." (PMID 32856862, 2020). "Furthermore, glutaminolysis and pentose phosphate pathways were upregulated when BRCA1 was depleted in ovarian cancer." (PMID 32470015, 2020). "Thus, in human patients, women who present BRCA1 and/or BRCA2 mutations have a very high lifetime risk of developing breast and ovarian cancer." (PMID 32005245, 2020). "Ovarian cancer cell lines with BRCA1 mutated and impaired HR (UWB1.289, SNU-251, OVCAR8) exhibit higher sensitivity towards PARPi, when compared with cells with wild-type or restored BRCA1 (SKOV3, A2780PAR and A2780CR)." (PMID 32316968, 2020). "With the introduction of PARP inhibitors for treating breast and ovarian cancers, the presence or absence of the germline BRCA1/2 pathogenic variant is being determined for appropriate drug selection." (PMID 33327492, 2020). "We performed amplicon sequencing of 144 cases who had breast/ovarian cancer disease (total 137 cases are patients and seven are tested for BRCA1/2 carrier) Using our custom designed gene panel consisting of 14 genes, that are associated with high to moderate risk of breast and ovarian cancers." (PMID 33552952, 2020). "However, variants in other genes besides BRCA1 and BRCA2 are associated with ovarian cancer predisposition, which would be missed by a genetic testing aimed only at indication for PARP inhibitor treatment." (PMID 33008098, 2020). "Testing of unselected ovarian cancer cases in non-Ashkenazi Jewish populations shows that the frequency of deleterious BRCA1 and BRCA2 variants ranged from 3–10% and 0.6–6%, respectively." (PMID 33086730, 2020).
ovarian carcinoma (continued). "Much is still also not known about the influence of individual genes on risk of ovarian cancer especially the contribution not explained by the BRCA1 and BRCA2 genes and the role of single nucleotide polymorphisms." (PMID 31099061, 2020). "In the previous study, patients with ovarian cancer who did not carry germline BRCA1/2 mutations also responded to PARP inhibitors, suggesting that the broader dysfunction of genes, such as a homologous recombination-deficient phenotype, is important." (PMID 32164585, 2020). "We found that breast and ovarian cancers from the clinical trial #NCT01623349, which carry BRCA1/2 germline mutation, as well as germline mutation carriers from TCGA database had a high TMB but did not score high on overall immune activity and PD-L1 expression relative to non-carriers." (PMID 32164626, 2020). "Germline or somatic mutations in HR genes other than BRCA1/2 have been reported in approximately 10% of ovarian carcinomas, including both serous and non-serous histologies." (PMID 31797087, 2020). "Based on oncogenetic counseling data, only one of the 16 BRCA1 hypermethylated patients had a first-degree relative with breast/ovarian cancer, indicating that these TNBC patients had likely been referred for screening based on young age rather than family history." (PMID 32719340, 2020). "The genetic test, including testing of BRCA1/2 mutation, in ovarian cancer patients had not been a standard practice in our country." (PMID 32856869, 2020). "An olaparib resistant cell line was generated from UWB1 cells that were treated with sustained, physiologically relevant 1μM concentrations of olaparib-containing cell media for 21 days to produce an olaparib-resistant, BRCA1 mutant ovarian cancer cell line named UWB1-R." (PMID 32098452, 2020). "Various guidelines recommend BRCA1/2 genetic tests of all ovarian cancers." (PMID 33327492, 2020). "Recent randomized studies on poly (adenosine diphosphate–ribose) polymerase inhibitors have demonstrated a substantial survival benefit in BRCA1/2 carriers, hence germline BRCA1/2 testing is becoming a mandatory in treatment decisions in advanced-stage ovarian cancer." (PMID 32131779, 2020). "Epidemiological studies suggest an inverse correlation between serum vitamin D (VD) levels and the risk of ovarian cancer, but there is a lack of data from BRCA1 mutation (BRCA1mut) carriers." (PMID 33227068, 2020). "Mutations in genes linked to HR (HR genes) have been reported in breast and ovarian cancers and in recent years, several studies have evaluated the consequences of the absence of BRCA1/2 expressions." (PMID 32481735, 2020). "Thus, to overcome past limitations, the goal of our study is to describe the punctual variants and copy number variations profile of BRCA1 and BRCA2 genes on Moroccan patients with breast and/or ovarian cancer suspected to have HBOC syndrome." (PMID 32778078, 2020). "After molecular analysis, we compared the histopathological characteristics between BRCA1/2 pathogenic mutations carriers and no carriers for breast and ovarian cancer cases separately." (PMID 32778078, 2020). "Analysis of ovarian cancer tissue from patients with HGSOC showed that loss of the normal copy of BRCA1/2 occurs in most germline BRCA1/2 mutations, indicating that this is an early event in HGSOC development." (PMID 32164585, 2020). "Moreover, germline BRCA1/2 carriers were more likely to have a family history of breast and/or ovarian cancer (p = 0.008)." (PMID 33194720, 2020). "BRCA1 and BRCA2 are the best-known genes associated with hereditary breast and ovarian cancer." (PMID 32046255, 2020). "M6620 was well tolerated in combination with carboplatin chemotherapy at biologically active doses, with the observation of clinical activity in patients with advanced solid tumors, including a patient with platinum-refractory and PARP inhibitor–resistant germline BRCA1 ovarian cancer." (PMID 32568634, 2020).